DMD (dystrophin)
Diseases named in the same sentence as DMD in open-access papers (continued):
Sharing a sentence is not in itself a finding about the gene and the disease.
Intellectual disability (29 papers, 2008 to 2025). "CNS dystrophin isoforms, including Dp427, Dp71, and Dp140, are associated with intellectual disabilities, anxiety, ADHD, autism spectrum disorder, and behavioral challenges, contributing to severe phenotypes." (PMID 40218127, 2025). "Despite not having affection for the IL1RAPL gene, which is responsible for intellectual disability and developmental delay, intellectual disability can have a heterogeneous cause and occur because of the deletion of the DMD gene, as it seems in this case." (PMID 41583306, 2025). "Fourteen isoforms have been thus identified for Dp71, the main intellectual disability-associated brain dystrophin, and at least eight of them are detected at substantial levels in the brain." (PMID 38802640, 2024). "Consistent with previous studies, individuals with DMD variants affecting all the brain isoforms of dystrophin were significantly more likely to have intellectual disability or poor academic performance compared to other groups." (PMID 38693632, 2024). "Mutations that affect expression of the other C-terminal brain forms of dystrophin have been associated with mental retardation." (PMID 26527530, 2015). "One third of DMD patients also have mental retardation (MR), likely due to mutations preventing expression of dystrophin and other brain products of the DMD gene expressed from distinct internal promoters." (PMID 19649270, 2008). "Notably, individuals with DMD variants affecting all the brain isoforms of dystrophin were significantly more likely to have intellectual disability or poor academic performance compared to other groups (p < 0.001)." (PMID 38693632, 2024). "They report 64% of individuals with mutations affecting Dp71 had intellectual disability compared with 25% of those with mutations affecting Dp260, Dp140 and Dp116, whilst only 15% of patients presented with intellectual disability when the mutations only affected full-length dystrophin." (PMID 31836945, 2020). "However, relevant genotype-phenotype analyses are missing to define whether cerebellar defects underlie the severe cases of intellectual deficiency that have been associated with genetic loss of the smallest product of the dmd gene, the Dp71 dystrophin." (PMID 29895670, 2018). "Interestingly, when mental retardation was associated with DMD, a disorganized cellular architecture was observed in post-mortem brains suggesting that dystrophin could be critical for the brain development in utero." (PMID 26568816, 2015). "Association between cognitive profile and prevalence of intellectual disability, ADHD, and ASD with mutation type in each dystrophin disruption groups." (PMID 36315559, 2022). "In this paper, we have described the case of a child affected by ASD, mild intellectual disability, DMD, and a history of febrile seizures, with a huge deletion of the proximal part of dystrophin gene." (PMID 34640386, 2021). "This is in line with our finding of mild intellectual disability in the presence of a deletion in the proximal region of the dystrophin gene." (PMID 34640386, 2021). "Among the genes with two hits uniquely in cases were three candidate genes linked to autism by a literature-curated database, DMD, SYNE1, and TBL1X and two genes implicated in schizophrenia (GRIK4) and intellectual disability (PQBP1)." (PMID 26185613, 2015). "Moreover, some of the DMD patients have comorbidities, including intellectual disability (up to 22% of patients), autism (up to 6%), and attention deficit disorders (up to 18%) due to disturbance of brain dystrophin-gene products." (PMID 40483693, 2025). "Prevalence of intellectual disability, ADHD, and ASD based in dystrophin disruption groups." (PMID 36315559, 2022). "The central location of both of these mutations in the dystrophin gene suggests that Dp71 is unaffected and that the individuals are not expected to display severe intellectual disability based on our knowledge of the genotype to phenotype ratio in DMD." (PMID 33188621, 2021).
Intellectual disability (continued). "Indeed, brain-muscle connections were also described before for the dystrophin gene, further extended to the autistic ADNP syndrome, with 96–100% of ADNP syndrome children suffering from motor impairments and with motor impairments correlated with intellectual disability in ADNP cases." (PMID 33086621, 2020). "Correlation between types of mutation (deletion, duplication, and point mutation) and severity of symptoms (ambulatory and non-ambulatory) with cognitive profiles and prevalence of intellectual disability and ADHD in each dystrophin disruption group were also analyzed." (PMID 36315559, 2022).
respiratory failure (21 papers, 2007 to 2026). The significant impairment of gas exchange within the lungs resulting in hypoxia, hypercarbia, or both, to the extent that organ tissue perfusion is severely compromised. "DMD genetic variants cause a spectrum of phenotypes, from severe progressive proximal muscle weakness and degeneration leading to wheelchair dependence and death from cardiac and/or respiratory failure to very mild muscular phenotypes; very rarely, cases are completely asymptomatic." (PMID 40313677, 2025). "As the disease progresses, patients suffering from DMD lose the ability to walk and ultimately die in the 2nd to 3rd decade of life, due to cardiac or respiratory failure." (PMID 34479633, 2021). "Impaired cough effort is common in the non-ambulatory stage of DMD causing atelectasis, pneumonia, and progression to respiratory failure." (PMID 39775224, 2025). "Lack of dystrophin results in progressive muscular degeneration, which impairs ambulation and causes mortality from cardiac and respiratory failure." (PMID 37830609, 2023). "Duchene muscular dystrophy (DMD) is caused by the absence of the protein dystrophin, which leads to muscle weakness, progressive degeneration, and eventually death due to respiratory failure." (PMID 33574358, 2021). "Absence of functional dystrophin results in muscle weakness and degeneration, eventually leading to cardiac and respiratory failure." (PMID 36372234, 2022). "Lack of functional dystrophin results in muscle weakness, degeneration, and as an outcome cardiac and respiratory failure." (PMID 34479633, 2021). "The DMD-edited microminipigs display characteristics consistent with human dystrophy, including the absence of the dystrophin protein, elevated serum creatine kinase activity, muscle fibre degeneration and regeneration, diminished locomotion, and sudden death resulting from respiratory failure." (PMID 38702481, 2024). "The lack of dystrophin in mdx CB was functional, since mdx mice had a defective peripheral chemosensory drive that would be predicted to contribute, alongside the well documented diaphragmatic pathology, to the respiratory failure." (PMID 23922741, 2013). "Due to the absence of dystrophin, DMD patients develop progressive muscle degeneration in the diaphragm, which often leads to respiratory failure and death." (PMID 17617925, 2007).
autism (20 papers, 2010 to 2025). Persistent deficits in social interaction and communication and interaction as well as a markedly restricted repertoire of activity and interest as well as repetitive patterns of behavior. "Dystroglycan, a central component of dystrophin complexes interacts with the autism-associated trans-synaptic neurexin-neuroligin complex, suggesting a putative mechanism underlying alterations in social behavior and/or communication in DMD." (PMID 26527530, 2015). "However, one patient with DMD and autism was shown to carry a submicroscopic deletion encompassing exons 12–25 of the dystrophin transcript, suggesting that the loss of Dp427 is sufficient to induce vulnerability to autism." (PMID 26527530, 2015). "Symptoms compatible with ASD and OCD, and Childhood Autism Rating Scale (CARS) scores were associated with genotype and impairment of cerebral isoforms of dystrophin." (PMID 40451248, 2025). "The finding of a significant SNP (rs721699 in the DMD gene) warrants mention in light of recent findings in which exon duplications in the DMD gene were found to give rise to an autism phenotype." (PMID 22050706, 2011). "Dystrophin is also found in the brain where aberrant expression leads to mental retardation in approximately one third of affected human patients, and memory deficits, autism, attention deficit hyperactivity disorder and behavioural problems have also been reported." (PMID 29474464, 2018). "One can only speculate if the autism was related to the dystrophin isoform in this one family." (PMID 26745801, 2016). "Most other “pathogenic” and “likely pathogenic” CNVs do not overlap nor appear similar to CNVs listed in Decipher, but they do span “autism genes” listed in the SFARI GENE, and AutismKB databases, such as DMD, NEXMIF, NLGN4X, PRKN, and others." (PMID 35762097, 2022).
muscle disorder (19 papers, 2008 to 2025). "Congenital myopathies and others like dystrophin causing muscle disorders that can affect both cardiac and skeletal systems." (PMID 38559672, 2024). "The most frequently studied muscular disease is Duchenne's muscular dystrophy (DMD), which is caused by mutations in the DMD gene (encoding dystrophin)." (PMID 35734962, 2022). "This statistic was confirmed in a presurvey conducted by our group, where we recruited 32 definite DMD carriers from the Zhejiang Muscular Disease (MD) care center and found that 50% of confirmed DMD carriers had increased CK activity." (PMID 33029525, 2020). "While primarily a muscle disorder, male patients with DMD can also have sleep, cognitive, and cortical abnormalities, thought to be driven by altered dystrophin expression in the brain." (PMID 38525359, 2024).
sarcoma (19 papers, 2011 to 2026). A usually aggressive malignant neoplasm of the soft tissue or bone. "DMD is a tumor suppressor implicated in the pathogenesis of many tumor types, such as lymphomas, sarcomas, and melanomas." (PMID 39338204, 2024). "Especially for DMD gene mutations and/or expression changes, numerous reports highlight a clear role in the pathogenesis in a wide range of cancers, including sarcomas, carcinomas, melanomas, lymphomas, and leukemia, as well as brain tumors." (PMID 35790299, 2022). "Significantly, the simultaneous loss of dystrophin and dysferlin or dystrophin and calpain-3 leads to a drastically increased sarcoma propensity, which is compatible with an additive TS function of these MD-related proteins." (PMID 35790299, 2022). "This genome remodeling finally produced targeted DMD deletions associated with replicative stress, isoform relocalization and metastatic spreading, exactly as observed in human myogenic sarcomas." (PMID 32438562, 2020). "Our model is considerably more conservative on the X chromosome and we do not infer any tumour suppressors on X. Out of eight homozygous deletions affecting DMD (encoding dystrophin), we observe seven in sarcomas." (PMID 29089486, 2017). "The importance of the DMD gene in tumorigenesis is supported by the finding that low DMD expression was associated with poor survival outcomes in patients with 15 different types of tumors (14 carcinomas and sarcoma)." (PMID 36900171, 2023). "Prior studies showed that the active X chromosome is targeted in human sarcomas with heterozygous or homozygous DMD mutations, suggesting that even heterozygous somatic DMD deletions in canine OS may result in complete gene inactivation." (PMID 31341965, 2019). "Thus, additional loss of both dysferlin and calpain-3 in dystrophin-deficient mdx mice dramatically reduced sarcoma latency." (PMID 21533183, 2011). "One-hundred and forty tumor cell lines were grouped into four groups based on their level of DMD expression (low or high) and their origin (carcinoma or sarcoma)." (PMID 36900171, 2023). "The GO Biological Process term regulation of cell migration was enriched (p = 0.02) in DEGs in sarcoma cell lines with low vs. high DMD expression." (PMID 36900171, 2023). "The two-class comparison analysis between cell lines with low vs. high DMD expression identified 998 DEGs for carcinoma, and 543 DEGs for sarcoma cell lines." (PMID 36900171, 2023). "The ranges for DMD expression for these cell lines were as follows (Unit: log2 (TPM + 1)): carcinoma cell lines with high (3.3–7.4) and low (0–0.01) DMD expression, sarcoma cell lines with high (4.07–7.6) and low (0–0.06) DMD expression." (PMID 36900171, 2023). "The calcium signaling pathway, which was enriched in the DEGs in more than 50% of primary tumors with low DMD expression, was also enriched in the DEGs in the comparison of sarcoma cell lines (p = 7.24 × 10−4)." (PMID 36900171, 2023). "These very pathways were enriched in the DEGs in more than 50% of primary tumors with low DMD expression, and also enriched in DEGs in carcinoma and sarcoma cell lines with low vs. high DMD expression." (PMID 36900171, 2023). "Similar to carcinoma cell lines, the following KEGG pathways were enriched in the DEGs in sarcoma cell lines with low DMD expression: ECM-receptor interaction (p = 0.048), PI3K-Akt signaling (p = 0.041), and cAMP signaling (p = 0.034)." (PMID 36900171, 2023). "Recently, recurrent somatic DMD deletions have been shown to drive development of aggressive sarcomas induced by fusion of immortalized myoblasts." (PMID 35790299, 2022). "We first review current knowledge on the incidence of STS in DMD patients and animal models before discussing wider evidence implicating DMD gene alterations in sarcoma patients." (PMID 33188621, 2021). "DMD was previously found to be recurrently deleted in canine OSA and has been implicated as a TSG in sarcomas in people." (PMID 33556121, 2021).
sarcoma (continued). "We highlight a clear role for DMD in the pathogenesis of several cancers, including sarcomas, leukaemia’s, lymphomas, nervous system tumours, melanomas and various carcinomas." (PMID 33188621, 2021). "In vivo, upon selection pressure, emerging tumors very frequently harbor DMD deletions similar to those described in human myogenic sarcomas." (PMID 32438562, 2020). "Since DMD inactivation by deletion has been reported to be a driver event in sarcomas with myogenic differentiation, we further characterized this highly frequent alteration." (PMID 32438562, 2020). "In the same study, they also showed that the frequency of CFS breaks correlates with its transcription level, thereby confirming that DMD deletion is particularly relevant in myogenic sarcomas or more widely in those derived from DMD-expressing cells." (PMID 31266185, 2019). "Analysis of 318 STS by CGH array evidenced a frequent deletion affecting the DMD gene (encoding dystrophin isoforms) in 16.5% of STS, including sarcomas with complex genomics, gastrointestinal tumors (GIST), and synovial sarcomas (SS)." (PMID 31266185, 2019). "To quantify the respective expression of DMD isoforms, we re-analyzed RNA-sequencing data from a cohort of 145 sarcomas previously published by our lab." (PMID 31266185, 2019). "To elucidate the oncogenic impact of DMD in sarcoma oncogenesis, we studied the genomic status of DMD in 318 sarcomas, mainly those with complex genomic profiles but alsosynovial sarcomas and GIST." (PMID 31266185, 2019). "In DMD-deleted human sarcomas, the Dp71 isoform is maintained, while the 427-kDa isoform is lost in high-risk tumors and is embedded in the FRAXC common fragile site." (PMID 31341965, 2019). "Some authors have suggested that DMD deletion is restricted to sarcomas with a myogenic differentiation." (PMID 31266185, 2019). "A recent study showed that the somatic DMD deletion is a common mechanism by which myogenic tumors progress to advanced sarcomas." (PMID 28947997, 2017). "In cancer, dystrophin suppresses many cell behaviors, such as cell migration, invasion, anchorage independence, in sarcomas with myogenic features." (PMID 28947997, 2017). "DMD is also a tumor suppressor in sarcomas, hematologic malignancies, and nervous system tumors." (PMID 40002695, 2025). "In addition, we included sarcoma (SARC) in this comparison because sarcomas originate from tissues (muscle and bone) known to express the DMD gene." (PMID 36900171, 2023). "Finally, the GO term, regulation of cell migration, was found to be in common with sarcoma cell lines with low DMD expression." (PMID 36900171, 2023). "However, a growing number of evidences links other neuromuscular dystrophies such as DMD to tumorigenesis (including sarcomas, carcinomas, melanomas, lymphomas, leukaemia, or brain tumors)." (PMID 36575500, 2022). "In the case of DMD inactivation in sarcomas, metastatic progression may be determined by the ratio of Dp427 to Dp71, a suggestion that warrants further investigation." (PMID 33188621, 2021). "Additionally, novel features of canine OS merit further exploration including the potential roles of SETD2 and DMD in sarcoma initiation and progression." (PMID 31341965, 2019). "Finally, dystrophin inhibits myogenic sarcoma cell migration, invasion, anchorage independence and invadopodia formation; and when deregulated, dystrophin restoration inhibits invasiveness and migration in sarcoma cell lines." (PMID 25143820, 2014). "Based on previously published known survival associations, sarcoma and HNSCC belong to the DMD‐suppressor group, since high DMD expression is associated with improved survival, while mesothelioma aligns with the DMD‐oncogenic group, since high DMD expression correlates with poorer survival." (PMID 40832923, 2026).